CFHR5 (complement factor H related 5)
Description:
Involved in complement regulation. The dimerized forms have avidity for tissue-bound complement fragments and efficiently compete with the physiological complement inhibitor CFH.
Synonyms: FHR-5; CFHL5; FHR5; CFHR5D
Tractability: Antibody: its Gene Ontology location is reachable by antibodies, with high confidence; UniProt places it where antibodies can reach, with medium confidence; UniProt predicts a signal peptide or a membrane-spanning region.
Gene: Protein-coding gene on chromosome 1 (196,975,010 to 197,009,678, forward strand). Ensembl gene ENSG00000134389.
Subcellular location: Secreted
Pathways (Reactome):
Immune System: Regulation of Complement cascade
Gene Ontology:
Molecular function: identical protein binding; protein binding; protein heterodimerization activity; complement component C3b binding
Biological process: positive regulation of complement activation; complement activation; complement activation, alternative pathway
Cellular component: protein-containing complex; extracellular region
Genetic constraint (gnomAD): Loss-of-function variants: 55 observed, 46.96 expected, observed/expected ratio (o/e) 1.17, 90% interval 0.94 to 1.47. The upper end of that interval is the gene's LOEUF score, 1.47, which puts it in group 6 of 6, group 1 being the genes least tolerant of losing a copy. Missense variants: 643 observed, 596.53 expected, observed/expected ratio (o/e) 1.08, 90% interval 1.01 to 1.15. Synonymous variants: 207 observed, 201.8 expected, observed/expected ratio (o/e) 1.03, 90% interval 0.92 to 1.15.
Homologues: Orthologues: chimpanzee CFHR5 (98% identical), macaque CFHR5 (88% identical), rabbit CFHR5 (68% identical), dog CFHR5 (64% identical). Paralogues in human: CFH (53% identical), CFHR2 (33% identical), CFHR1 (32% identical), CFHR4 (30% identical), F13B (28% identical), CFHR3 (24% identical), PAPPA2 (18% identical), CSMD3 (18% identical), CSMD2 (17% identical), PAPPA (17% identical), CSMD1 (17% identical), SVEP1 (16% identical), and 27 more.
Diseases named in the same sentence as CFHR5 in open-access papers:
CFHR5 is named in the same sentence as 63 diseases in open-access papers, as found by Europe PMC text mining. Sharing a sentence is not in itself a finding about the gene and the disease. The quoted sentences say what the papers report.
Nephropathy (27 papers, 2011 to 2025). A nonspecific term referring to disease or damage of the kidneys. "THBS1, implicated in tubulointerstitial remodeling and inflammation, and CFHR5, associated with renal disease progression, were significantly upregulated in the FD group." (PMID 41301692, 2025). "The mechanism that causes kidney disease in CFHR5 nephropathy has recently been demonstrated in humanised mice that expresses the human mutant FHR5 and FH." (PMID 34379175, 2021). "A rare subtype of familial C3 glomerulopathy caused by AP dysregulation, CFHR5 nephropathy, shares many clinical and histological features with IgAN." (PMID 34379175, 2021). "CFHR5 nephropathy is an autosomal dominant condition, and, to date, all reported cases have been heterozygous for the CFHR5 mutation." (PMID 33753502, 2021). "This hereditary endemic form in Cyprus was named CFHR5-nephropathy, which is caused by an internal duplication of exons 2 and 3 of the CFHR5 gene." (PMID 34566977, 2021). "Recently, a subtype of C3 glomerulonephritis was linked to a mutation and internal duplication in the CFHR5 gene and this disease entity was termed CFHR5 nephropathy." (PMID 25855355, 2015). "In CFHR5 nephropathy, the mutation results in the duplication of the dimerization motif and enables generation of large complexes that have enhanced deregulation." (PMID 24161036, 2013). "A rare, recently described variant of C3GN is CFHR5 nephropathy, a monogenic disease caused by mutations in the gene encoding complement factor-related protein 5 (CFHR5)." (PMID 23227086, 2012). "Our report is to our knowledge the first description of the association of kidney disease with a heterozygous sequence variant causing frameshift and premature truncation of CFHR5." (PMID 22503529, 2012). "Previously, mutations in complement factor H, CD46 (membrane cofactor protein) and factor I were identified among patients with biopsy-proven C3GN, but CFHR5 nephropathy is the first description of C3GN associated with a mutation in the CFHR5 gene." (PMID 21114651, 2011). "Similarly, a study of patients with CFHR5 nephropathy with duplication of exons 2 and 3 in CFHR5 demonstrated that the mutant variant exhibited decreased binding to chicken RBCs." (PMID 37955705, 2024). "There were no familial cases of C3G or CFHR5 gene variants belonging to CFHR5 nephropathy." (PMID 34476601, 2022). "Indeed, low CFHR5 levels in an individual with a CFHR5 frameshift mutation were associated with renal disease development after Streptococcus pneumoniae infection." (PMID 36194022, 2022). "To elucidate how abnormal FHR proteins cause C3G, we modeled CFHR5 nephropathy in mice." (PMID 33753502, 2021). "In CFHR5 nephropathy, multiplex-ligation probe amplification enabled the identification of a novel heterozygous mutation in the CFHR5 gene involving internal duplication of the initial two N-terminal SCRs in two affected families originally from the Troodos region of Cyprus." (PMID 24161036, 2013). "In this report, we show data according to which a reduction of hsa-mir-1207-5p binding ability on its target site in the 3′UTR of HBEGF due to the presence of C1936T SNP is associated with the severity of CFHR5 nephropathy in patients inheriting the pathogenic CFHR5 gene duplication of exons 2–3." (PMID 22319602, 2012). "This hypothesis has derived from reports of genetic variation in CFHR5 and susceptibility to kidney disease." (PMID 22503529, 2012). "However, we are aware of two other incompletely characterized cases with the CFHR5 mutation and renal disease, in which good allograft function was evident one decade after deceased donor renal transplantation." (PMID 21114651, 2011). "Genetic variants in CFHR5 have been mostly associated with C3 glomerulopathy and one subtype of the disease is termed CFHR5-nephropathy." (PMID 37955705, 2024).
Nephropathy (continued). "We modeled CFHR5 nephropathy in vivo by generating mouse strains that expressed hFH with either the normal FHR5 protein or FHR5mut, the abnormal FHR5 protein associated with CFHR5 nephropathy." (PMID 33753502, 2021). "Genetic mutations that increase the hetero-dimerisation of FHR5, and thereby increase the ability to compete with FH ligand, are strongly associated with a familial C3 glomerulopathy referred to as CFHR5 nephropathy." (PMID 34379175, 2021). "Specific forms of FHR-5 protein can be disease-modifying in C3G, as seen in CFHR5 nephropathy, but the role of missense variations and frameshift mutations needs further investigation." (PMID 34566977, 2021). "The prototypical example is CFHR5 nephropathy, through which an internal duplication within a single CFHR5 gene generates a mutant FHR5 protein (FHR5mut) that leads to accumulation of complement C3 within glomeruli." (PMID 33753502, 2021). "The classic example was identified in Greek Cypriot patients with C3GN (often called CFHR5 nephropathy) that results from a mutant FHR5 protein encoded by a CFHR5 gene with an internal duplication of exons 2 and 3 (FHR51,2-FHR5)." (PMID 34211499, 2021). "To elucidate the role of FHR5mut in CFHR5 nephropathy and to investigate the role of FHR5 in glomerular C3 regulation, we generated delFH-FHR mouse strains that transgenically coexpressed hFH with either wild-type FHR5 or FHR5mut." (PMID 33753502, 2021). "A heterozygous mutation in FHR5 is associated with a familial form of C3G, known as CFHR5 nephropathy." (PMID 31701048, 2019). "In this context, it is intriguing that two very similar FHR-5 proteins result in different clinical entities (CFHR5 nephropathy or DDD)." (PMID 30050540, 2018). "In patients with CFHR5 nephropathy, duplication of exons 2 and 3 of the CFHR5 gene leads to a novel CFHR5 protein with 11 SCR." (PMID 27200326, 2016). "Based on genetic studies, FH-related protein 5 (CFHR5) is implicated in glomerular diseases, such as atypical hemolytic uremic syndrome, dense deposit disease, and CFHR5 nephropathy." (PMID 25855355, 2015). "Using this Ab, CFHR5 was detected in glomerular immune deposits in several kidney diseases, for example, membranous nephropathy, IgA nephropathy, lupus nephritis, focal glomerular sclerosis, and postinfectious glomerulonephritis." (PMID 25855355, 2015). "Polymerase chain reaction (PCR) using genomic DNA isolated from peripheral blood monocytes and serum CFHR5 western blot analysis revealed the presence of the heterozygous internal duplication in the CFHR5 gene, confirming the diagnosis of CFHR5 nephropathy." (PMID 21114651, 2011). "Complement factor H-related protein 5 (CFHR5) nephropathy is a familial renal disease endemic in Cyprus." (PMID 21114651, 2011). "This unique case demonstrates that renal-derived CFHR5 protein cannot prevent the development of CFHR5 nephropathy." (PMID 21114651, 2011). "CFHR5 is a 65 kDa protein composed of nine SCRs, and the internal duplication in exons 2 and 3 characteristic of CFHR5 nephropathy results in an expressed protein with duplicated SCRs 1 and 2 respectively." (PMID 21114651, 2011). "Complement factor H related gene 5, CFHR5, whose post-treatment downregulation shows a strong association with increased PFS times, is highly expressed in liver cells, while its allelic variants show statistical association with nephropathies." (PMID 31355141, 2019). "Recognizable entities within C3 glomerulopathy include those with characteristic morphologic appearances (DDD and electron-dense intramembranous GBM transformation) and those with clear etiology (complement factor H-related 5 [CFHR5] nephropathy and the presence of an abnormal CFHR5 protein)." (PMID 24161036, 2013). "Interestingly, the inheritance of the miRSNP 1936T allele was significantly associated to chronic renal failure in a cohort of 78 patients diagnosed with complement factor H-related protein 5 (CFHR5) nephropathy (also known as C3-glomerulopathy)." (PMID 24204837, 2013).
Nephropathy (continued). "Here we hypothesized that miRSNPs might act as genetic modifiers predisposing to a milder or more severe disease on the background of a primary inherited glomerulopathy, such as TBMN and/or CFHR5 nephropathy." (PMID 22319602, 2012). "The presence of the CFHR5 sequence variant in the mother and sister of the index patient (neither of whom had overt evidence of kidney disease) indicates that heterozygosity for this CFHR5 sequence variant is not sufficient to cause kidney disease." (PMID 22503529, 2012). "Affected individuals have a heterozygous internal duplication in the CFHR5 gene, although the mechanism through which this mutation results in renal disease is not understood." (PMID 21114651, 2011). "Importantly, three recent reports showed that CFHR1, CFHR2, and CFHR5 deregulate complement by competing with FH for binding to C3b, and thus they may rather enhance complement activation in human renal diseases." (PMID 25855355, 2015). "The recurrence of CFHR5 nephropathy in an unrelated kidney demonstrates that local synthesis of normal CFHR5 by the kidney is not sufficient to prevent disease." (PMID 21114651, 2011). "We detected glomerular FHR5, C3, and C5b-9 in 2 cases of CFHR5 nephropathy, 1 with and 1 without glomerular inflammation and clinical signs of glomerulonephritis." (PMID 31701048, 2019). "A specific model for CFHR5 nephropathy was also developed, in which mice lacking mFH and murine FHRs but coexpressing human FH and mutant FHR-5 (with duplicated CCP1-2) developed glomerular deposition of C3 fragments, while those coexpressing human FH and wild type FHR-5 did not." (PMID 38410512, 2024).
C3 glomerulopathy (12 papers, 2013 to 2026). "Genetic variants in CFHR5 have been detected in patients with complement-mediated kidney disease such as aHUS, C3 glomerulopathy, and immune complex-associated membranoproliferative glomerulonephritis." (PMID 37955705, 2024). "d) In nearly all males and females who carry heterozygous mutations in the CFHR5 gene, which are responsible for an inherited form of C3 glomerulopathy." (PMID 25514610, 2014).
atypical hemolytic-uremic syndrome (8 papers, 2012 to 2024). A rare, genetic thrombotic microangiopathy due to dysregulation of the alternative complement pathway and characterized by the triad of hemolytic anemia, thrombocytopenia, and acute renal dysfunction. "Sequence and copy number variations in the CFHR gene cluster (CFH, CFHR1, CFHR2, CFHR3, CFHR4 and CFHR5) are linked to atypical hemolytic uremic syndrome (aHUS) and C3 glomerulopathy." (PMID 38772735, 2024). "Variations in the CFHR5 gene were also found in patients with atypical hemolytic uremic syndrome and membranoproliferative glomerulonephritis type II/dense deposit disease." (PMID 25855355, 2015). "While defective CFHR5 may contribute to atypical hemolytic uremic syndrome, CFHR1 has been shown to be downregulated in tissue from LUAD tumors compared to healthy adjacent tissue." (PMID 36544145, 2022). "Interestingly, the same variant that we describe was reported in an individual serving as a control in a study investigating the role of CFHR5 in atypical hemolytic uremic syndrome." (PMID 22503529, 2012). "We chose these two CFHR5 variations because these were the most abundant CFHR5 alterations identified in our patients suffering from IC-MPGN or C3G (and atypical hemolytic uremic syndrome)." (PMID 34566977, 2021).
glomerular diseases (7 papers, 2013 to 2021). "Thus, CFHR5 may locally enhance complement activation via interference with the complement-inhibiting function of FH, by enhancement of C1q binding, and by activating complement, thereby contributing to glomerular disease." (PMID 25855355, 2015).
IgA nephropathy (6 papers, 2018 to 2026). "Transcriptomic-wide MR identified candidate genes across GN subtypes: RECQL, BRSK2, and MGP in acute GN; AFM, CFHR5, and EPHB2 in chronic GN; IL6R, MBL2, and PRSS3 in IgA nephropathy; and TIMP4, HCK, and PEAR1 in membranous nephropathy." (PMID 41990104, 2026). "In recent years, genetic analysis of CFHR5 in several conditions such as atypical hemolytic uremic syndrome (aHUS), IgA-nephropathy (IgAN), or MPGN explored a potential connection with these pathological states, but the exact pathophysiological role of FHR-5 is still unknown." (PMID 34566977, 2021).
age-related macular degeneration (5 papers, 2009 to 2025). Age-related loss of vision in the central portion of the retina (macula), secondary to retinal degeneration. "Among these, one can mention SNP rs34533956 in the gene CFHR5, which is associated with age-related macular degeneration (Narendra, Pauer & Hagstrom, 2009)." (PMID 28289571, 2017). "This study in the Finnish population reveals genetic reduction of the complement factor CFHR5 as enhancing retinal health and reducing the risk for age-related macular degeneration (AMD), suggesting new strategies for AMD prevention and treatment." (PMID 40593839, 2025).
glomerulonephritis (4 papers, 2011 to 2021). A renal disorder characterized by damage in the glomeruli. "Notably, serum CFHR5 levels also were found to be decreased in individuals with biopsy-proven C3 glomerulonephritis." (PMID 22503529, 2012).
C3 glomerulonephritis (3 papers, 2012 to 2021). Glomerulonephritis characterized by C3 accumulation with little or absent deposition of immunoglobulin, in the absence of ultrastructural electron-dense transformation seen in dense deposit disease. "A heterozygous CFHR5 mutation has been shown to be associated with the development of familial C3 glomerulonephritis in individuals of Cypriot ancestry, and allelic variants of CFHR5 have been associated with dense deposit disease." (PMID 22503529, 2012).
chronic kidney disease (3 papers, 2012 to 2021). Impairment of the renal function secondary to chronic kidney damage persisting for three or more months. "In summary, we have identified a heterozygous sequence variant causing frameshift and premature truncation of CFHR5 in an individual with chronic kidney disease after streptococcal infection." (PMID 22503529, 2012). "We speculate that it was the presence of both the heterozygous CFHR5 sequence variant and streptococcal infection that precipitated chronic kidney disease in our index patient." (PMID 22503529, 2012). "We speculate that this heterozygous CFHR5 sequence variant is a risk factor for the development of chronic kidney disease after streptococcal infection." (PMID 22503529, 2012).
COVID-19 (3 papers, 2022 to 2025). A disease caused by infection with severe acute respiratory syndrome coronavirus 2. "Hub proteins for post-COVID-19 individuals included cytastatin 3 (CST3), Notch homolog 1, translocation-associated (NOTCH1), complement factor H-related 5 (CFHR5), and ST6 beta-galactoside alpha-2,6-sialyltransferase 1 (ST6GAL1)." (PMID 36405747, 2022). "However, radar plots revealed a clear decrease in the average abundance of several complement proteins in IVIG-treated patients compared to both COVID-19 controls and healthy donors, including C1RL, CFD, CD5L, C8G, and CFHR5." (PMID 40821834, 2025).
lupus nephritis (3 papers, 2018 to 2025). Glomerulonephritis in the context of systemic lupus erythematosus. "The levels of CFHR3 and CFHR5 found in plasma were higher in patients with lupus nephritis than in healthy individuals, and patients with both high CFHR3 and high CFHR5 exhibited the shortest progression-free survival." (PMID 35095896, 2021). "Similarly, CFHR5, has been found elevated in SLE, lupus nephritis and ankylosing spondylitis, a chronic inflammatory rheumatic disease, where it holds potential diagnostic and prognostic value." (PMID 40918143, 2025).
autoimmune disease (2 papers, 2020 to 2025). A disorder resulting from loss of function or tissue destruction of an organ or multiple organs, arising from humoral or cellular immune responses of the individual to their own tissue constituents. "In addition, high concentrations of CFHR5 were observed in the plasma of patients with systemic lupus erythematosus, an autoimmune disease." (PMID 32518534, 2020).
venous thromboembolism (2 papers, 2023 to 2025). Occlusion of the lumen of a vein by a thrombus that has migrated from a distal site via the blood stream. "Further supporting these findings, studies in venous thromboembolism (VTE) have observed elevated levels of complement factor H-related protein 5 (CFHR5), a regulator of the C3 alternative pathway, in patients with acute VTE." (PMID 41187099, 2025).
colorectal carcinoma (1 paper, 2023). A malignant epithelial neoplasm that arises from the colon or rectum and invades through the muscularis mucosa into the submucosa. "CFHR5, a complement activating protein, has been identified as a significant factor in the development of liver metastasis originating from primary tumors of colorectal carcinoma." (PMID 37953280, 2023).
diabetes (1 paper, 2025). "Following adjustment for age, sex, BMI, alcohol consumption status, vascular/heart diseases, diabetes, medications for cholesterol, blood pressure, or diabetes, and exogenous hormone use, CD55, CFHR4, and CFHR5 were found to exhibit significant associations with AMD." (PMID 40735363, 2025).
diabetic nephropathy (1 paper, 2009). "It is noteworthy here that the presence of the CFHR protein, CFHR-5, has been detected in 92 out of 100 biopsies from patients with glomerular sclerosis from all causes, including diabetic nephropathy, focal glomerular sclerosis and advanced proliferative glomerular diseases with areas of sclerosis." (PMID 19411110, 2009).
haemolytic uraemic syndrome (1 paper, 2021). "CFHR5 mutation was considered the cause of atypical haemolytic uraemic syndrome." (PMID 33874952, 2021).